ZNF70 (zinc finger protein 70)
Description:
May be involved in transcriptional regulation.
Synonyms: Cos17; MGC48959
Tractability: PROTAC: ubiquitination databases record sites on it.
Gene: Protein-coding gene on chromosome 22 (23,738,682 to 23,751,730, reverse strand). Ensembl gene ENSG00000187792.
Subcellular location: Nucleus
Subcellular location (Human Protein Atlas): Cytosol
Pathways (Reactome):
Gene expression (Transcription): Generic Transcription Pathway
Gene Ontology:
Molecular function: protein binding; DNA-binding transcription factor activity, RNA polymerase II-specific; RNA polymerase II transcription regulatory region sequence-specific DNA binding
Biological process: regulation of transcription by RNA polymerase II
Cellular component: cytoplasm; megasporocyte nucleus; nucleus
Genetic constraint (gnomAD): Loss-of-function variants: 18 observed, 39.87 expected, observed/expected ratio (o/e) 0.45, 90% interval 0.31 to 0.67. The upper end of that interval is the gene's LOEUF score, 0.67, which puts it in group 2 of 6, group 1 being the genes least tolerant of losing a copy. Missense variants: 506 observed, 598.08 expected, observed/expected ratio (o/e) 0.85, 90% interval 0.79 to 0.91. Synonymous variants: 219 observed, 230.99 expected, observed/expected ratio (o/e) 0.95, 90% interval 0.85 to 1.06.
Homologues: Orthologues: chimpanzee ZNF70 (99% identical), macaque ZNF70 (99% identical), dog ZNF70 (91% identical), pig ZNF70 (87% identical), rabbit ZNF70 (83% identical), guinea pig ZNF70 (81% identical), Drosophila melanogaster CG3281 (29% identical), Drosophila melanogaster CG2712 (25% identical), Drosophila melanogaster Phs (24% identical). Paralogues in human: ZNF805 (45% identical), ZFP37 (44% identical), ZNF529 (43% identical), ZNF35 (43% identical), ZNF266 (43% identical), ZNF264 (43% identical), ZNF582 (42% identical), ZNF599 (42% identical), ZNF619 (42% identical), ZNF69 (42% identical), ZNF404 (41% identical), ZNF778 (41% identical), and 50 more.
Diseases named in the same sentence as ZNF70 in open-access papers:
ZNF70 is named in the same sentence as 6 diseases in open-access papers, as found by Europe PMC text mining. Sharing a sentence is not in itself a finding about the gene and the disease. The quoted sentences say what the papers report.
gastric cancer (2 papers, 2021 to 2022). A primary or metastatic malignant neoplasm involving the stomach. "In addition, miR-1269a can inhibit the expression of tumor suppressor gene ZNF70, while miR-1269a rs73239138 can up-regulate ZNF70, thereby reducing the susceptibility to gastric cancer." (PMID 35252180, 2022).
colon cancer (1 paper, 2024). "Similarly, it has been shown that Zinc finger protein 70 increases the IL-1β secretion in macrophages, promoting colon cancer cell proliferation (HCT-116)." (PMID 39769450, 2024).
colorectal cancer (1 paper, 2025). A primary or metastatic malignant neoplasm that affects the colon or rectum. "Considering that ZNF70 expression is elevated in colorectal cancer (CRC), ZNF70 could be a promising target for CRC treatment." (PMID 40307577, 2025).
esophageal squamous cell carcinoma (1 paper, 2020). Esophageal squamous cell carcinoma (ESCC) is a type of esophageal carcinoma (EC) that can affect any part of the esophagus, but is usually located in the upper or middle third. "In esophageal squamous cell carcinoma (ESCC), miR-574-5p was upregulated both in vitro and in vivo which correlated with ZNF70 expression." (PMID 35006436, 2020).
ovarian carcinoma (1 paper, 2026). A malignant neoplasm originating from the surface ovarian epithelium. "Collectively, our findings reveal tsRNA-Ala-3-0030 as a previously unrecognized oncogenic regulator that promotes ovarian cancer progression through ZNF70 downregulation." (PMID 41695344, 2026). "Mechanistically, tsRNA-Ala-3-0030 directly targeted the tumor suppressor ZNF70, leading to its downregulation and consequent promotion of ovarian cancer growth and metastasis." (PMID 41695344, 2026).
tumor (1 paper, 2022). "MiR-574-5p is increased both in human ESCC tissues and cell lines, which serves as a tumor promoter: promotes proliferation and inhibits apoptosis by targeting ZNF70 via mitochondrial-mediated ROS generation and MAPK pathways." (PMID 36311195, 2022).